EPO (erythropoietin)
Diseases named in the same sentence as EPO in open-access papers (continued):
Sharing a sentence is not in itself a finding about the gene and the disease.
anemia (continued). "Abnormal fluctuations of EPO leading to disruptions in RBC lifespan could also be in the origin of anemia in such seemingly disparate situations as spatial flights or malaria infections." (PMID 38191841, 2024). "Reduced erythropoietin levels have been correlated with fetal anemia." (PMID 39492784, 2024). "Anemia, a well-known comorbidity in patients with CKD, is associated with several factors including inflammation; deficiency in iron, vitamin D, and other factors; and resistance to erythropoietin (EPO)." (PMID 39763572, 2024). "Based on these findings, the multi-compound formulation of SDT appears to influence the hematopoietic system by enhancing serum erythropoietin expression and stimulating the bone marrow, which could benefit patients with anemia." (PMID 39338353, 2024). "Recombinant erythropoietin (rHuEPO) has heralded a transformative era in anaemia management, particularly among chronic renal failure patients, engendering increased survival rates, reduced hospitalizations, enhanced cognitive function, and elevated quality of life." (PMID 39184703, 2024). "High concentrations of ceramides in male O3KO and O1/3dKO mice may potentially reduce androgen levels, thereby dampening the stimulatory effect that androgens have on erythropoietin, leading to decreased hemoglobin levels and anemia." (PMID 38715613, 2024). "The production of RBCs in the bone marrow is controlled by erythropoietin (EPO), a hormone mainly produced and secreted by the kidneys in response to hypoxia and anemia, which binds to its receptor (EPOR) on the surface of erythroid progenitors in the bone marrow." (PMID 39666728, 2024). "CKD patients may experience anemia due to various factors, including decreased erythropoietin (EPO) production, shortened red blood cell survival, inflammation, hemolysis, blood loss and nutritional deficiencies." (PMID 38672265, 2024). "Although clinically less strong than that performed in the US, this study provided the green light to start the procedures necessary to obtain authorization from the European Medicines Agency (EMEA) to use EPO for the treatment of anemia of patients with kidney failure in Europe." (PMID 38672425, 2024). "This assessment is based on the finding that day 1 serum EPO levels were not significantly linked to anemia in the univariate logistic regression analysis." (PMID 38792868, 2024). "It is plausible that EPO elevation could be a result of renal hypoperfusion, hypoxia, anemia, or a hepato-protective and regenerative mechanism mediated by EPO." (PMID 38610814, 2024). "Although not proven, supportive care with hematinic supplementation and erythropoietin stimulating agents may have aided in limiting the severity of the anemia." (PMID 39238534, 2024). "Along with marketing approval, the FDA also awarded Epogen “orphan drug” status under an Act that provided companies with incentives to develop drugs to treat rare diseases and had approved the use of EPO for the treatment of anemia in HIV-infected patients receiving zidovudine (AZT)." (PMID 38672425, 2024). "A poor erythropoietin response in inflammatory states and malnutrition leads to anemia." (PMID 38649863, 2024). "EPO is also used to treat various diseases, although it may exert adverse effects in patients with anemia and chronic heart failure, such as elevated blood pressure, thrombosis, and seizures (Rao, Binbrek & Sobel, 2008)." (PMID 39624122, 2024). "Irbesartan may contribute to anemia through direct inhibition of erythropoietin or insulin-like growth factor-1 production, or indirectly by improving renal perfusion and subsequently reducing oxygen consumption." (PMID 39635439, 2024). "Our study represents the pioneering network meta-analysis (NMA) to evaluate both direct and indirect impacts of various doses of daprodustat, recombinant human erythropoietin (rhEPO), and placebo on anemia in dialysis-dependent chronic kidney disease (CKD) patients." (PMID 38828426, 2024).
anemia (continued). "SCD mice treated with SGLT‐2 inhibition demonstrated increased erythropoietin which could explain improvements in anaemia." (PMID 39267208, 2024). "The higher frequency of anemia among dogs of later grades of AKI may be related to several factors such as reduction of circulating EPO, severity of azotemia, and oliguria." (PMID 38787184, 2024). "Other possible treatments could be the administration of blood growth factors or erythropoietic growth factors, like erythropoietin, for a possible better recovery of patients with anemia." (PMID 38393145, 2024). "Moreover, renal insufficiency results in reduced EPO production due to the kidneys’ diminished capacity for hypoxia detection and EPO synthesis, leading to anemia, a frequent complication in chronic kidney disease." (PMID 38764792, 2024). "Randomised controlled trials have supported the European approval of epoetin alfa for treating symptomatic anaemia in adults with low or intermediate-1 risk primary MDS, specifically for patients with serum erythropoietin (EPO) levels below <200 IU/L and haemoglobin (Hb) levels ≤100 g/L." (PMID 39463913, 2024). "Additionally, the compliance of patients on dialysis with anemia was negatively affected by the parenteral and subcutaneous routes of administration of iron supplements, EPO, and ESAs." (PMID 38828426, 2024). "Anemia of inflammation has been identified as an inflammatory process responsible for impaired iron metabolism, proliferation of erythrocytes, and production and signaling of EPO." (PMID 38787184, 2024). "However, mechanisms such as uninfected erythrocyte (uE) lysis, dyserythropoiesis, iE and uE phagocytosis, iron restriction, and impaired erythropoietin (EPO) synthesis were also described to contribute to anemia in SM patients." (PMID 38297098, 2024). "The potential mechanisms involved in the association between anemia and CKD are various and complex, including the decreased production of endogenous erythropoietin (EPO), deficiency of absolute and/or functional iron, and inflammation with the hepcidin levels increased." (PMID 38586465, 2024). "EPO stimulates the proliferation and differentiation of erythroid progenitor/precursor cells; it is therefore believed that stress responses in acute anemia are mainly governed by the committed progenitor and/or precursor levels, but the contribution of HSCs is unclear." (PMID 39284836, 2024). "During erythropoiesis, in response to anemia mediated by hypoxia-inducible factor-2α or exogenous EPO administration, enhancement of ERFE synthesis, which is encoded by the FAM132B gene in erythroblasts, inhibits HEP-25 production, and thus promotes iron acquisition, storage, and utilization." (PMID 39179496, 2024). "Further, GCs can aid in the treatment of EPO-resistant anemia by stimulating progenitor self-renewal, while, in healthy humans, GC injection also accelerates erythropoiesis and increases total hemoglobin mass, which may help to prevent altitude sickness." (PMID 39474425, 2024). "In hypothyroidism, normocytic normochromic anemia is a frequent clinical condition since thyroid hormones stimulate the proliferation of erythrocyte precursors both directly and via the enhancement of erythropoietin production." (PMID 40729266, 2024). "Primarily, we lacked data regarding the impact(s) of inflammation, anemia and EPO on RDW, precluding detailed analysis of the underlying mechanisms linking these factors with RDW." (PMID 38434056, 2024). "Anemia may result from impairment of erythropoietin formation as heavy metals like cadmium deposit in the kidney and liver and hamper erythropoietin production." (PMID 38784687, 2024). "Erythropoietin has also shown an increase in response to tissue hypoxia and may be considered a marker of anemia-induced renal hypoxia." (PMID 38395758, 2024).
anemia (continued). "Currently available treatments for anemia in patients receiving anticancer treatments include blood transfusions, iron supplementation, and erythropoiesis-stimulating agents (ESAs), like recombinant EPO (rhEPO) and darbepoetin-α." (PMID 38628673, 2024). "Transfusion and/or erythropoietin may be used to manage anemia, while the use of growth factors may be appropriate for neutropenia." (PMID 38534939, 2024). "Consequently, the dual roles of EPO, serving as a crucial treatment for anemia and potentially contributing to bone fragility, necessitates a thorough exploration in patients with ESRD undergoing hemodialysis." (PMID 39835325, 2024). "Nevertheless, anemias are frequently caused by a nutritional deficiency of either iron or vitamins, including CKD-related anemia, which is also partly caused by nutritional deficiencies in addition to a functional erythropoietin deficiency or inflammation." (PMID 39685765, 2024). "We also advocate for the use of anemia-directed agents such as erythropoietin and analogs (in patients with endogenous erythropoietin < 125 units/L), danazol, or luspatercept in combination with ruxolitinib to try to maintain ruxolitinib dose intensity rather than reduce the dose of ruxolitinib." (PMID 38441783, 2024). "It is thought that the effects of hormones (especially testosterone) on erythropoietin activity coupled with the higher pre‐ and post‐natal growth rate found in boys may play a role in the observed prevalence of severe anaemia in male children." (PMID 39525391, 2024). "Renal patients, especially those with moderate-to-severe chronic kidney disease (CKD) are prone to hematological abnormalities, especially severe anemia, mainly due to the reduced secretion of erythropoietin and impaired erythrocyte survival in the uremic toxic environment." (PMID 39336553, 2024). "The treatment of CKD-induced anemia is done primarily using recombinant EPO." (PMID 39502472, 2024). "Furthermore, the complex interaction between EPO and FGF-23 is discussed, as well as their association with other anemia-related factors and processes such as Klotho, vitamin D, and iron deficiency." (PMID 39684548, 2024). "The other possible causes might be related to the activation of pro-inflammatory cytokines suppress erythropoietin response to anemia and shorten RBC half-life." (PMID 39689160, 2024). "Furthermore, it was observed that in the Siwu plus EPO group, oxidative stress and inflammatory factors were inhibited, resulting in improved renal function and anemia." (PMID 39911241, 2024). "Low erythropoietin levels hinder the production of red blood cells, thereby contributing to anemia." (PMID 39839624, 2024). "A drastic reduction in the quantity and quality of daily exercise will reduce the possibility of erythropoietin production by skeletal muscle and could be an additional factor aggravating other factors that can lead to anemia in cirrhotic patients." (PMID 39124795, 2024). "Anemia, a deficiency of red blood cells, is also often present in advanced CKD due to the combination of impaired red blood cell survival deficiency of production of erythropoietin by the kidney, and impaired bone marrow responsiveness to erythropoietin." (PMID 39763936, 2024). "Anemia in SARS-CoV-2 infection may be related to cytokine-induced inhibition of erythropoietin synthesis and may lead to the increased need for mechanical ventilation." (PMID 38610597, 2024). "Additionally, anemia brought on by decreased erythropoietin production increases heart load, which can result in cardiac muscle hypertrophy and even heart failure." (PMID 39685552, 2024). "For anemia treatment in cancer patients, human recombinant erythropoietin is often used." (PMID 38978080, 2024). "Furthermore, the overactivation of the Renin–Angiotensin–Aldosterone System (RAAS) plays a crucial role in the progression of both cardiac and renal diseases, contributing to the worsening of anemia through mechanisms such as erythropoietin resistance." (PMID 39685694, 2024).
anemia (continued). "Moreover, hypertension is closely associated with chronic kidney disease, which often leads to anemia because the kidneys are the primary site of erythropoietin production." (PMID 38549043, 2024). "Malaria-induced anemia is exacerbated by increased hepcidin, which impairs iron absorption, reducing both iron availability for the parasite and red blood cell formation, despite elevated erythropoietin." (PMID 39492784, 2024). "This can cause both anemia and high RDW by reducing erythropoietin production." (PMID 38633310, 2024). "Anaemia is a predictive factor for the progression ofkidney disease, whereas erythropoietin has a direct renal protective effect.Therefore, both anaemia and erythropoietin deficiency may contribute to diabetickidney damage." (PMID 39139439, 2024). "It was speculated that supplementation of EPO to treat anemia in T-ALL patients requires assessing the risks and benefits." (PMID 38464517, 2024). "In terms of anaemia management, although usage of erythropoietin-stimulating agents (ESA) was relatively lower in HHD patients compared to in-centre HD, we did not report any statistically significant differences between both modalities in haemoglobin levels, ESA usage, or weekly units of ESA." (PMID 36819955, 2023). "According to the CDC, the United States has more than 37 million American adults with CKD, with more than one out of every seven people suffering from anemia due to CKD.The currently available treatment option for anemia due to CKD is erythropoietin-stimulating agents (ESA) and iron supplementation." (PMID 38021836, 2023). "Iron supplementation or recombinant EPO have been used to improve anemia in these patients." (PMID 37629516, 2023). "Several mechanisms are contributed to the onset and aggravation of anemia, including comorbid kidney diseases, blunted erythropoietin synthesis/response, hemodilution, cytokine-mediated inflammation, some guideline-recommended medications, and disturbances in iron metabolism." (PMID 37794317, 2023). "Another study suggested that anemia may have resulted from insufficient production of erythropoiesis-stimulant erythropoietin in the kidney." (PMID 36873867, 2023). "Our study therefore aimed to evaluate the outcomes of IV iron monotherapy and as combination therapy with rHuEPO for the early correction of postoperative anemia following orthopedic surgery, to better our understanding of the relationship between erythropoietin, iron metabolism, and erythropoiesis." (PMID 37464433, 2023). "Research conducted on rats has indicated that using EPO to treat anemia could impact the development of kidney dysfunction." (PMID 38022248, 2023). "The physiopathological mechanisms of anemia, such as the reduction of endogenous erythropoietin and the decrease in oxygen transport, are leading to tissue hypoxia, peripheral vasodilation, stimulating neurohormonal activity, and maintenance of the progressive renal and cardiac dysfunction." (PMID 37374094, 2023). "HF causes renal failure because of the reduced output and may ultimately induce anemia by decreasing the secretion of endogenous erythropoietin leading to a vicious cycle called cardio-renal-anemia syndrome." (PMID 37794317, 2023). "Further studies to investigate the neutralizing effect anti-EPO antibodies could have on EPO in the development of anaemia would be essential." (PMID 36989322, 2023). "Erythropoietin (EPO) deficiency is a predominant cause of anemia in chronic kidney disease (CKD), but anemia could be also caused by the complication of CKD." (PMID 36724056, 2023). "Thus, when EPO is increased by anemia/hypoxia, ERFE expression by erythroid progenitors is upregulated, and the protein is released into the circulation." (PMID 36835406, 2023). "Furthermore, iron chelation with DFP, in addition to decreasing parenchymal iron deposition, restores hepdicin:iron responsiveness, partially reverses anemia, and normalizes serum EPO concentration in MDS mice." (PMID 38153418, 2023).
anemia (continued). "For instance, stimulation of erythropoiesis—by bleeding, anemia, hypoxia, or injection of exogenous EPO—strongly suppresses hepcidin production in mice and humans, and iron absorption increases, often dramatically, during such stress erythropoiesis to accommodate increased iron demand." (PMID 37578340, 2023). "Treatment of anemia due to chronic kidney disease with agents increasing erythropoietin (EPO) from erythropoietin producing cell (EPC) by inhibition of one of the enzymes causing degradation of hypoxia inducible factor (HIF) (HIF prolyl hydroxylase inhibitor (HIF-PHI)) is gaining popularity." (PMID 37346300, 2023). "Further studies are required to clarify the synergistic effects of daprodustat and dapagliflozin, which correct chronic kidney disease-related anemia by promoting endogenous erythropoietin production and normalizing iron metabolism to manage low-risk MDS in the long term." (PMID 36975732, 2023). "A decrease in erythropoietin production in the peritubular cells of the kidney was a major factor that could lead to anemia." (PMID 37305144, 2023). "LC or creatine supplementation provides an effective adjuvant or therapeutic regimen that significantly reduces oxidative and inflammatory stress and erythropoietin-resistant anemia and evades comorbidities such as tiredness, impaired cognition, muscle weakness, myalgia, and muscle wasting." (PMID 36836532, 2023). "While malaria parasite growth and development within RBCs and immune pressure cause hemolysis of RBCs, resulting in low Hb and anemia in malaria cases, low Hb in HIV is caused by bone marrow suppression, suppression of erythropoietin, and direct effects leading to RBC loss." (PMID 37568487, 2023). "Moreover, treating anemia with erythropoietin-stimulating agents improves energy and the physical function in non-dialysis CKD patients." (PMID 37754834, 2023). "Assessment of anti-EPO antibodies in pregnancy may contribute to the understanding of the pathophysiology of P. falciparum malarial anaemia, and influence treatment guidelines especially in severe anaemia." (PMID 36989322, 2023). "Altered end-organ response to circulating testosterone or EPO, reduced erythropoietic reserve or decreased marrow reactivity may account for the observed increase in anemia with age, particularly in older men." (PMID 37240288, 2023). "Additionally, 18 (9.4%) patients were treated with recombinant human erythropoietin or received dose adjustments for moderate anemia." (PMID 38093592, 2023). "The rising prevalence of anemia due to CKD has been driving the global demand for EPO drugs." (PMID 37631301, 2023). "In fact, we are aware that PTH may have several extra-mineral negative effects in dialysis patients, spanning from increased left ventricular hypertrophy and higher blood pressure to erythropoietin-resistant anemia and poor nutrition and quality of life." (PMID 37351832, 2023). "As a result, anemia was corrected, resulting in reduced levels of EPO." (PMID 38328786, 2023). "In CKD, declining kidney function results in reduced EPO production, leading to anemia." (PMID 38276262, 2023). "Further analysis revealed that this anemia could potentially be attributed to the underutilization of erythropoietin (EPO)." (PMID 37803046, 2023). "Furthermore, albuminuria is a risk factor for anemia in the CKD; this is mainly due to reduced erythropoietin formation in the kidneys." (PMID 36901179, 2023). "In addition, the significant delay of EPO therapy in patients with RBV treatment failure likely contributed to a higher number of relevant anemia, RBV dose reduction and, as a consequence, more relapses or an incomplete viral clearance." (PMID 37375540, 2023). "In addition, TNFα can induce anemia in patients with MM by directly inhibiting the formation and differentiation of red blood cells, reducing sensitivity to erythropoietin (EPO), and promoting IL-6 secretion by myeloma cells." (PMID 37250588, 2023).